MPO (myeloperoxidase)
Diseases named in the same sentence as MPO in open-access papers (continued):
Sharing a sentence is not in itself a finding about the gene and the disease.
Obesity (continued). "The negative association between ISM1 and MPO suggests that the all-circulating levels of ISM1 in children with obesity might have a non-adipose cell origin." (PMID 36595188, 2023). "However, the strong effect of both urinary lactulose and fecal MPO on FGF21 and FGF23, adipokines associated with increased intestinal permeability in mice and obesity in humans, suggests a complex interrelationship between these risk factors in the early pathogenesis of MetS." (PMID 36096405, 2022). "The increased levels of plasma MPO, neutrophil activation marker CD66b, and calprotectin, mainly originating from neutrophils, in individuals with obesity as compared to lean controls sustain the relationship between obesity and systemic activation of neutrophils." (PMID 34207683, 2021). "The association between MPO and T2D and obesity was not statistically significant." (PMID 32277104, 2020). "The existing literature to date paints a complex and often conflicting picture of the interplay between leptin, VEGF, MPO, CRP, and microvascular function in obesity." (PMID 40900465, 2025). "In participants with obesity, we observed significantly elevated inflammatory marker (TNF-α and IL-6), myeloperoxidase, leptin, and insulin levels (p < 0.05)." (PMID 39700087, 2024). "Thus, MPO impairs vascular function via PVAT inflammation and suppression of vasoprotective mediators, making it a potential therapeutic target in obesity-related cardiovascular disease." (PMID 40252642, 2025). "Compared with eutrophic male mice, those with HFD-induced obesity displayed higher levels of cfDNA/MPO complexes in white adipose tissue but not in plasma." (PMID 39861371, 2025). "MPO, a heme-peroxidase predominantly expressed by neutrophilic granulocytes, accumulates in PVAT as part of an obesity-related adipose tissue inflammation and exerts detrimental effects on the vasculature via alteration of PVAT adipocyte signature and expression profile." (PMID 40252642, 2025). "In contrast to these findings, baseline MPO was herein not significantly increased in individuals with obesity, as compared to controls, and was negatively correlated with WHR." (PMID 38685051, 2024). "Nonetheless, to the current researchers’ knowledge, no studies have yet been conducted to investigate the effects of physical activity, without dietary intervention, on MPO levels and on the MPO/PON1 ratio in obesity." (PMID 37887393, 2023). "Two recent clinical trials noted that there is an increase in mitochondrial ROS production, as well as in the inflammatory enzyme myeloperoxidase (MPO), among females with PCOS, and the concentrations were even higher among those who presented with obesity and insulin resistance." (PMID 37569074, 2023). "We therefore hypothesize that activated MMP-9 and MPO reflect important disease mechanisms in PWS which goes beyond disrupted carbohydrate metabolism and obesity." (PMID 37430349, 2023). "It has been observed that MPO and XOD increased in patients with obesity and MetS." (PMID 35883817, 2022). "Other described released mediators by neutrophils on obesity were IL‐8, MMP‐9 or MPO." (PMID 35818731, 2022). "First, the mechanism of ANGPTL6 and MPO in obesity or T2D was not identified due to the cross-sectional design of the study." (PMID 32277104, 2020). "Indeed, in the early stage of obesity, neutrophils infiltrating adipose tissue lead to release of different substances like free radicals, TNF-α, and MPO." (PMID 32963689, 2020). "Thus, future studies should evaluate the beneficial effects of targeting MPO and ANGPTL6 simultaneously for the treatment of both obesity and T2D by inhibiting the activity of MPO and overexpression of ANGPTL6." (PMID 32277104, 2020). "MPO and CRP may contribute to impaired microvascular function in obesity." (PMID 40900465, 2025). "Interestingly, MPO levels were elevated in boys with obesity or overweight, but not in their female counterparts." (PMID 39857642, 2024).
Obesity (continued). "Furthermore, HFD up-regulated MPO in the intestine of obesity-prone rats but not in obesity-resistant rats, suggesting that HFD-induced obesity, not HFD alone, is associated with intestinal inflammation." (PMID 23091640, 2012). "Therefore, we anticipate that obesity may not significantly alter the ratio of free-to-bound MPO, though this remains an intriguing question for future research." (PMID 40252642, 2025). "Studies that investigate abluminal effects of MPO on the vessel wall, and particularly on the function of PVAT as an imbalanced endocrine organ in obesity, are lacking." (PMID 40252642, 2025). "After classifying patients with T2D according to obesity status, our findings showed that both plasma ANGPTL6 and MPO levels were significantly higher in obese than in non-obese diabetic patients." (PMID 32277104, 2020). "There is an effect of obesity status but not diet on liver ARG-1, MPO, and SREBP-1 expression." (PMID 38075211, 2023).
periodontitis (75 papers, 2003 to 2026). An acute or chronic inflammatory process that affects the tissues that surround and support the teeth. "Both periodontitis and severe COVID share elevated cfDNA/MPO-DNA levels associated with NET-mediated inflammatory responses." (PMID 41463036, 2025). "Elevated MPO levels have been consistently associated with various inflammatory conditions, including periodontitis, reflecting the abundance and activity of neutrophils within the periodontal tissues." (PMID 39954018, 2025). "MPO-DNA levels positively correlate with probing depths and clinical attachment loss, with the highest levels seen in individuals with periodontitis and rheumatoid arthritis." (PMID 41463036, 2025). "The increase in MPO concentration is associated with oral inflammation and is characteristic of periodontitis." (PMID 30901933, 2019). "In the present study, periodontitis-challenge was associated with a significant increase in MPO activity." (PMID 31682614, 2019). "Application of PAR agonist peptide to gingiva has induced periodontitis in rats (radiographically assessed bone loss, myeloperoxidase (MPO) activity)." (PMID 22899931, 2012). "In support of this, an association between active MMP-8 and myeloperoxidase has recently been reported during chronic periodontitis progression." (PMID 22436166, 2012). "Subjects designated as so-called 'rapid acetylators' (bearing at least one wild-type allele NAT2*4) or bearing the highly expressed MPO variant (homozygous -463 G/G) are at an increased risk of periodontitis when smoking." (PMID 19570260, 2003). "Furthermore, research should investigate salivary MPO's potential as a cardiovascular risk predictor in periodontitis." (PMID 38852177, 2025). "Studies have shown dramatic elevation of MPO levels in periodontitis, suggesting that MPO could be a useful diagnostic marker for the activity of the acute inflammation." (PMID 30669541, 2019). "It has been shown that MPO/MMP-8 could represent the discriminatory biomarkers for the site specific diagnosis of periodontitis, and their association might reflect the disease severity." (PMID 30669541, 2019). "Experimental periodontitis induces bone loss and an increase in the gingival MPO and plasmatic CRP." (PMID 30304126, 2018). "Smokers with the high activity variant of NAT 2 and MPO are at an increased risk of periodontitis." (PMID 20170537, 2010). "However, high levels of MPO in gingival crevicular fluid are associated with increased oxidative stress and tissue degradation, making this enzyme a possible indicator of deleterious inflammatory activity in periodontitis." (PMID 41304258, 2025). "Other proteins that stand out are neutrophil defensin 1, annexin A1, lysozyme C, resistin, cathepsin G, myeloperoxidase, and azurocidin, which were upregulated between 2.8 and 25.1-fold in periodontitis." (PMID 40384977, 2025). "Several meta-analyses have demonstrated that chronic periodontitis has been shown to elevate systemic oxidative stress and increase myeloperoxidase activity in saliva and gingival crevicular fluid." (PMID 41463003, 2025). "Among the main biomarkers that have been studied for the diagnosis of periodontitis are proteolytic enzymes released by neutrophils, such as myeloperoxidase (MPO) and MMPs." (PMID 41304258, 2025). "Elevated salivary aMMP‐8 and MPO levels, alongside worse clinical periodontal parameters in MetS‐periodontitis participants compared to systemically healthy individuals, signify heightened neutrophil activity and oxidative stress in metabolic syndrome." (PMID 38852177, 2025). "Participants with MetS and periodontitis exhibited significantly higher periodontal parameters, salivary aMMP‐8, and MPO (26.26 vs. 24.1 ng/mL and 13.53 vs. 11.55 ng/mL compared to systemically healthy periodontitis patients) (all p < 0.01)." (PMID 38852177, 2025).
periodontitis (continued). "This study investigated the effect of metabolic syndrome (MetS) on periodontal clinical parameters and salivary biomarkers' matrix metalloproteinase‐8 (MMP‐8) and myeloperoxidase (MPO) in patients with periodontitis." (PMID 38852177, 2025). "The selected salivary biomarkers (citH3, ELA, CALPRO, and MPO) were used to identify differences between healthy periodontium and periodontitis." (PMID 41425261, 2024). "The analysis of MPO allowed us to assess the systemic effects of periodontitis and PBM, extending beyond local gingival inflammation." (PMID 39765779, 2024). "Experimental studies examining the effect of PBM on MPO activity in periodontitis have reported findings like ours." (PMID 39765779, 2024). "The benefit of our case-control study was the use of multiple salivary biomarkers (citH3, ELA, CALPRO, and MPO), thus distinguishing between the biomarkers with the greatest impact on periodontitis groups." (PMID 41425261, 2024). "For saliva, MPO levels differ significantly between systemically healthy periodontitis patients and control subjects." (PMID 37569455, 2023). "In preclinical studies, verbascoside was able to inhibit levels of Bax, Bcl-2, nuclear factor-κB, iNOS, and myeloperoxidase, showing anti-inflammatory benefits in a model of periodontitis." (PMID 35406100, 2022). "Myeloperoxidase (MPO) expression was measured by IHC in inflamed gingival tissues from periodontitis patients (n = 12)." (PMID 36527111, 2022). "Correlations between Vanins and clinical parameters, PD and CAL; between Vanins and inflammation, IL1B; and between Vanins and MPO in periodontitis were investigated by Spearman's correlation analysis respectively." (PMID 36527111, 2022). "A previous study observed a difference in MPO concentration between healthy and chronic periodontitis group." (PMID 32503210, 2020). "In our study, administration of anti-HMGB1 antibody in a murine periodontitis model inhibited myeloperoxidase (MPO) activity, neutrophil migration, and bone resorption in a dose-dependent manner." (PMID 32760399, 2020). "Increased levels of myeloperoxidase and superoxide dismutase, which are among the main regulators of inflammation, were found in periodontitis." (PMID 31195790, 2019). "Beneficial effects of adjunctive SDD therapy is likely to be related to the reduced levels of two major periodontitis-associated MMPs, MMP-8 and -9, and their potential oxidative activator MPO." (PMID 30669541, 2019). "Nevertheless, further investigation and randomized control trials are needed to confirm or discard the possible relationship between the elevation of MMP-9 and MPO levels in samples of patients with periodontitis and T2D." (PMID 31355267, 2019). "Due to the intense inflammatory process present in ligature-induced periodontitis, there is an increase of MPO activity in the gingival tissue." (PMID 29680842, 2018). "Ex vivo evidence from progressive chronic periodontitis in humans supports a role for MPO in direct activation of latent MMP-8 and MMP-9, and the inactivation of TIMP-1." (PMID 28218665, 2017). "When comparing MPO activity in gingivitis and periodontitis groups, the p value was 0.059 and the mean difference between these 2 groups was 0.148 (95% CI = [−0.004]–[0.302]) which was considered as clinical significant value." (PMID 27274868, 2016). "Significant difference in salivary MPO activity was found between periodontitis patients and periodontally healthy individuals (p = 0.003)." (PMID 27274868, 2016). "By contrast, elevated MPO activity is able to predict periodontitis from healthy and gingivitis subjects (OR = 36.23, 95% CI = 1.20–1097.66, p = 0.039)." (PMID 27274868, 2016). "In the present study, the highest MPO activity was observed in saliva from periodontitis patients, followed by gingivitis patients and finally periodontally healthy individuals." (PMID 27274868, 2016).
periodontitis (continued). "The results showed that salivary MPO activity in periodontitis patients was significantly higher than in healthy subjects (p = 0.003) and higher than in gingivitis patients (p = 0.059)." (PMID 27274868, 2016). "It has been demonstrated that GCF levels of MPO and MMP-8 and associations between them were related to development and treatment responses in patients with chronic periodontitis." (PMID 26132583, 2015). "Significantly, both in PLS patients and combined periodontitis patients (AP + CP) the levels of MPO correlated well with amount of detected HNP1-3 (PLS: r = 0.742, p = 0.035; CP + AP: r = 0.533, p = 0.004)." (PMID 25260376, 2014). "The group with periodontitis that was treated with the high dose of Atorvastatin (10 mg/kg) showed a significant reduction in the concentration of MPO (p<0.01)." (PMID 24130702, 2013). "In fact, our results showed that, in rats compromised by the experimental periodontal disease, the myeloperoxidase activity was significantly higher at the sites of the chronic periodontitis, when compared to that of naive animals." (PMID 20069116, 2009). "Furthermore, metformin reversed the elevated expression of C3 and MPO in periodontitis, compared to the periodontitis and ddH2O groups." (PMID 40801798, 2025). "Meanwhile, in rats with glucocorticoid-induced osteoporosis submitted to periodontitis, ATV at 27 mg/kg decreased bone loss, reduced myeloperoxidase (MPO), TNF-α, IL-1β, IL-6, and IL-8, and increased IL-10, glutathione (GSH), superoxide dismutase (SOD), and catalase (CAT) levels." (PMID 39476053, 2024). "Changes in GPX, the glutathione/oxidized glutathione ratio, myeloperoxidase (MPO) activity, lipid peroxides, and other markers in periodontitis patients indicate that an increase in GPX may be an antioxidative compensation in response to oxidative stress." (PMID 38802844, 2024). "Increased level of MPO was noted in saliva in patients with periodontitis." (PMID 36949424, 2023). "Moreover, various studies found that rats with experimental periodontitis had high MPO activities in the gingival tissue compared to the control group." (PMID 34586188, 2021). "GCF levels of MPO and NE were reported to be increased in smokers (Sm) with periodontitis." (PMID 34360367, 2021). "Gingival crevicular fluid (GCF) levels of these enzymes were reported to be increased in periodontitis suggesting that MPO, BGD, and NE may be potential markers of periodontal inflammation." (PMID 34360367, 2021). "The exaggerated NETs formation, which is often found in an aggressive form of periodontitis, can cause tissue destruction by NET-bound proteins and enzymes, such as neutrophil elastase or MPO and concomitant release of cytotoxic molecules and has a crucial role in the pathogenesis of periodontitis." (PMID 33391628, 2020). "Therefore, in this study, we aimed to evaluate the effects of diode laser treatment on the inflammatory cell infiltration and MPO level in the periodontium when applied adjunctive to SRP in an experimental periodontitis rat model." (PMID 30020350, 2018). "However, other studies have also reported that MPO levels were elevated in the sera, salivary, and gingival crevicular fluid of patients with periodontitis compared with control individuals." (PMID 29394286, 2018). "On the other hand, MPO activity levels are higher in hepatic tissue samples of obese individuals.We believe that the steatosis caused by periodontitis in rats is self-limiting, not advancing to steatohepatitis." (PMID 29680842, 2018). "The elevation of circulating levels of CarP and NETs may reflect the increased concentration of MPO in the sera, salivary, gingival crevicular fluid, and periodontal tissue of in patients with periodontitis." (PMID 29394286, 2018).